POGK (pogo transposable element derived with KRAB domain)
Synonyms: LST003; KIAA15131; BASS2; KRBOX2
Tractability: PROTAC: UniProt records ubiquitination sites on it; ubiquitination databases record sites on it; its protein half-life has been measured.
Gene: Protein-coding gene on chromosome 1 (166,839,314 to 166,860,347, forward strand). Ensembl gene ENSG00000143157.
Subcellular location: Nucleus
Subcellular location (Human Protein Atlas): Nucleoplasm
Gene Ontology:
Molecular function: protein binding; DNA binding; nucleic acid binding
Biological process: regulation of DNA-templated transcription
Cellular component: nucleoplasm; nucleus
Genetic constraint (gnomAD): Loss-of-function variants: 15 observed, 55.09 expected, observed/expected ratio (o/e) 0.27, 90% interval 0.18 to 0.42. The upper end of that interval is the gene's LOEUF score, 0.42, which puts it in group 1 of 6, group 1 being the genes least tolerant of losing a copy. Missense variants: 513 observed, 831.62 expected, observed/expected ratio (o/e) 0.62, 90% interval 0.57 to 0.66. Synonymous variants: 270 observed, 318.25 expected, observed/expected ratio (o/e) 0.85, 90% interval 0.77 to 0.94.
Homologues: Orthologues: chimpanzee POGK (99% identical), macaque POGK (99% identical), pig POGK (96% identical), dog POGK (95% identical), guinea pig POGK (94% identical), rabbit POGK (91% identical), mouse Pogk (91% identical), rat Pogk (91% identical). Paralogues in human: JRKL (14% identical), TIGD1 (14% identical), TIGD6 (14% identical), TIGD4 (13% identical), TIGD5 (13% identical), JRK (13% identical), TIGD2 (13% identical), CENPB (12% identical), TIGD7 (12% identical), POGZ (11% identical), TIGD3 (11% identical).
Diseases named in the same sentence as POGK in open-access papers:
POGK is named in the same sentence as 8 diseases in open-access papers, as found by Europe PMC text mining. Sharing a sentence is not in itself a finding about the gene and the disease. The quoted sentences say what the papers report.
hepatocellular carcinoma (2 papers, 2022 to 2023). A malignant tumor that arises from hepatocytes. "In conclusion, our study pointed out that POGK has a high diagnostic value for hepatocellular carcinoma, and the high expression of POGK is closely related to the poor prognosis of HCC pa-tients." (PMID 36421335, 2022). "Herein, we evaluated the prognostic significance of POGK expression in patients with hepatocellular carcinoma (HCC)." (PMID 36421335, 2022). "Currently, the only reported study on POGK gene indicates its upregulation in hepatocellular carcinoma patients and correlates with poor prognosis and immune cell abundance in the tumor microenvironment, suggesting it as an effective therapeutic target for this patient population." (PMID 38048229, 2023).
autism spectrum disorder (1 paper, 2023). A spectrum of developmental disorders that includes autism, and Asperger syndrome. "POGZ has been associated with intellectual disability and autism spectrum disorders, and plays a role in modulating chromatin structure; however, the biological role of POGK is unknown." (PMID 36688327, 2023).
breast carcinoma (1 paper, 2025). "Immunohistochemical analysis revealed reduced POGK expression in breast cancer tissues compared to normal samples, with a marked decrease in TNBC relative to non‐TNBC subtypes." (PMID 39814373, 2025). "They analyzed a group of transposable‐element‐derived genes (TEGs) across diverse cancer cohorts from the Cancer Genome Atlas (TCGA), identifying POGK as the top‐altered TEG transcript, most significantly dysregulated in breast cancers." (PMID 39814373, 2025).
tumor (4 papers, 2022 to 2025). "For example, target genes of ETV2 and POGK, which are associated with cell differentiation and tumor angiogenesis, were specifically expressed in the uterus from the estrogen group." (PMID 39872660, 2024). "Univariate analysis using logistic regression demonstrated that POGK expression was associated with clinicopathologic characteristics, typically associated with tumor aggressiveness." (PMID 36421335, 2022). "How do the tumor‐suppressive functions of POGK‐iso1 manifest in TNBC subtypes or other tumor types, and to what extent is POGK expression predictive of patient survival or treatment response?" (PMID 39814373, 2025). "Identifying the molecular players that regulate this isoform balance will be critical for developing therapeutic strategies to restore the tumor‐suppressive POGK iso1 expression." (PMID 39814373, 2025). "Meanwhile, POGK expression correlated with the abundance of immune cells in the tumor microenvironment of HCC." (PMID 36421335, 2022). "High expression of POGK significantly correlated with tumor status (p = 0.036), race (p = 0.025), weight (p = 0.002), body mass index (BMI, p = 0.033), histologic grade (p < 0.001), and alpha-fetoprotein (AFP, p < 0.001)." (PMID 36421335, 2022). "Herein, we substantiated that POGK gene expression correlated with the abundance of immune cells in the tumor microenvironment of HCC, suggesting it can be a potent therapeutic target for this patient population, emphasizing the need for more studies." (PMID 36421335, 2022). "Moreover, we further analyzed the correlation between POGK and immune infiltration in the tumor microenvironment." (PMID 36421335, 2022). "POGK was significantly upregulated in HCC and correlated with tumor status (p = 0.036), race (p = 0.025), weight (p = 0.002), body mass index (p = 0.033), histologic grade (p < 0.001), and alpha-fetoprotein (p < 0.001)." (PMID 36421335, 2022). "describe a tumor‐suppressor function of POGK in triple‐negative breast cancer (TNBC), the most aggressive subtype with very few known therapeutic targets." (PMID 39814373, 2025). "showing that POGK, a gene derived from the pogo DNA transposon, has tumor‐suppressor functions in triple‐negative breast cancer." (PMID 39814373, 2025). "in Molecular Cell that identify Pogo transposon‐derived gene POGK as tumor suppressor in triple‐negative breast cancer (TNBC) by regulating ribosome biogenesis and restricting cell growth." (PMID 39814373, 2025).
cancer (2 papers, 2015 to 2025). A tumor composed of atypical neoplastic, often pleomorphic cells that invade other tissues. "The authors observed that POGK levels are both upregulated and downregulated across various cancer cohorts, raising another important question." (PMID 39814373, 2025). "In conclusion, the study provides compelling insights into the mechanism of action of POGK, highlighting how its isoform switching undermines cancer defense mechanisms." (PMID 39814373, 2025). "With the growing focus on pharmacological inhibition of splicing factors and on isoform switching drugs, correcting POGK isoform imbalance in TNBC offers a promising strategy to combat this aggressive cancer subtype." (PMID 39814373, 2025).
POGK also shares sentences with these, for which no sentence is quoted: endometrial cancer (1 paper); hepatitis C (1); Intellectual disability (1).